CD4 (CD4 molecule)
Diseases named in the same sentence as CD4 in open-access papers (continued):
Sharing a sentence is not in itself a finding about the gene and the disease.
periodontal disease (continued). "It has been suggested that the level of immunosuppression or the decrease in the CD4+ T cell count determines the progression of periodontal disease." (PMID 23258979, 2012). "Patients with low CD4+ T‐cell counts or recent therapy initiation may require closer monitoring and preventive interventions to mitigate periodontal disease progression." (PMID 41287475, 2025). "Periodontal diseases severity has correlation with CD4+ cells depletion rate in HIV." (PMID 38638482, 2024). "Although a certain understanding of the role of different CD4+ T cell subsets in periodontal diseases is achieved, further studies are still in progress for the identification of the core mechanisms that regulate the differentiation and activation of CD4+ T helper cells." (PMID 35222410, 2022). "mTOR signaling could promote Th1 and Th17 cell differentiation and inhibit Treg commitment through different mTOR complexes, therefore we anticipate a regulation effect of mTOR signaling on periodontal diseases by regulating CD4+ T cell subsets." (PMID 35222410, 2022). "The complex interaction between hPDLSCs and CD4+ T lymphocytes might have an implication in pathological states, particularly in periodontal disease." (PMID 32423044, 2020). "Besides innate immunity, cells of the adaptive immunity act in the pathogenesis of periodontal diseases, specially CD4+ and CD8+ T cells (T-helper (Th) cells)." (PMID 32960889, 2020). "Recently, we have shown that type-1 IFNs play a major role in the pathogenesis of periodontal disease by disrupting innate immunological functions, constitutively priming CD4+ T-cells by DCs leading to elevated RANKL expression and, subsequently, alveolar bone loss." (PMID 29922275, 2018). "In particular, tumor necrosis factor-α (TNFα) and interferon-gamma (IFNγ) are believed to promote bone degradation in periodontal disease, because periodontal tissues in patients with periodontitis are infiltrated by CD4+ and CD8+ T cells, which produce these cytokines." (PMID 30158833, 2018). "With the aim to identify high risk populations so as to set up better preventive measures, the present study tested the hypothesis that periodontal disease in persons living with HIV was significantly related to low CD4/CD8 ratio and an increase in plasma viral load." (PMID 33308188, 2020). "ET-P also showed significantly elevated CD4+T-cell count and CD8+T-cell count, consistent with studies in HIV patients and those with periodontal disease, where Prevotella abundance correlated positively with CD4+T-cell count and CD8+T-cell count." (PMID 41244669, 2025). "The immunological parameter usually used for this evaluation is the CD4/CD8 T-lymphocyte counts in peripheral blood and plasma viral load, which appear to play an important role in the progression of periodontal disease and the course of HIV-infection." (PMID 33308188, 2020). "A relationship between smoking and periodontal disease with dental mobility was found (p = 0.04), duration of treatment (p = 1.53e-3), and with age (p = 0.02) but not type of treatment, viral load, or CD4+ T cell count." (PMID 36813599, 2023). "We also calculated the total number of identified cells (CD66b+, CD4+, CD8+, CD56+, CD68+, Siglec8+, CD138+) and OSCC patients showed significantly more cells (55,966 ± 22,151) compared to periodontal disease (32,550 ± 11,816) and control patients (6,355 ± 4,733)." (PMID 35048057, 2021). "Similar to caries, CD4 count and VL did not influence the presence of periodontal disease with adjustment of other factors among PHIV youth." (PMID 27299992, 2016). "In an animal study, IFN-γ was associated with enhanced alveolar bone loss mediated by RANKL-expressing CD4(+) Th cell in response to A. actinomycetemcomitans during the progression of periodontal disease and a concomitant and significantly increased coexpression of IFN-γ in RANKL(+) CD4(+) Th cells." (PMID 24151615, 2013).
periodontal disease (continued). "According to the results of our study, although aspirin use reduced macrophage, CD4 + T-lymphocyte, and CD8 + T-lymphocytes amount in the ACS + P group, it did not clinically affect periodontal disease severity (similar to BOP) and CD4 + / CD8 + ratio." (PMID 38451305, 2024).
primary immunodeficiency (33 papers, 2013 to 2026). "Laboratory test results found that the CD4/CD8 ratio was higher in patients with primary immunodeficiency disease (1.8 vs. 0.6, P = 0.022)." (PMID 38997717, 2024). "The current Working Definitions for Clinical Diagnosis of Primary Immunodeficiency recommend studying FoxP3 expression in CD4+CD25hi cells." (PMID 38077340, 2023). "Primary immunodeficiency was diagnosed in 1.4% of the patients, and was notable for two cases of idiopathic CD4+ lymphocytopenia and one case of IFN-γ autoantibodies identified during the patient’s follow-up." (PMID 34198597, 2021). "Thyroid hormone and estrogen signaling, hepatitis B and MAPK pathways were enriched in CD4+ T cells from RA, while primary immunodeficiency pathway was significantly enriched in SLE." (PMID 34079550, 2021). "At first diagnosis of primary immunodeficiency the male patient presented normal T cell counts and a subsequently performed peripheral blood lymphocyte phenotyping showed normal CD4+ T cell and CD45RA+ naïve CD4+ T cell counts." (PMID 30987377, 2019). "Here, we investigated the qualitative dynamics of the naïve CD4+ T-cells in both health and in disease in primary immunodeficiencies." (PMID 28448599, 2017). "In the present study, we identified an upregulation of CD4 in the LN group, implying that this helper T cell may be involved in the primary immunodeficiency which characterizes nutrient restriction." (PMID 39273192, 2024). "Moreover, CD4 and CD8 were associated with the primary immunodeficiency pathway in KEGG, which implies a potential link between MNR and defective immunity in the Wagyu fetal thymus." (PMID 39273192, 2024). "Indeed, CD4+ T cells play an important role in host defense against Mycobacteria spp., as evidenced by susceptibility of patients with HIV or primary immunodeficiencies such as SCID or IL-12- or IFN-γ-deficiency." (PMID 30524426, 2018). "However, patients with primary immunodeficiency in ICOS have reduced numbers of circulating CXCR5+ CD4+ T cells." (PMID 26333070, 2015). "The CD4 and CD8 T-cell count as well as the ratio between the two with the IHG represent an additional consideration that can be applied to the diagnostic process for primary immunodeficiencies including CVID, which has been historically assessed with a focus on B-cell function." (PMID 39728019, 2024). "GSEA analysis adds more insight into the 23 ERBB2-related DEGs and primary immunodeficiency signaling pathway, showing that ERBB2-related DEGs associated with primary immunodeficiency were mainly down-regulated ERBB2-related DEGs, such as CD79A, CD19, CD3D, CD3E, CD8A, and CD4." (PMID 36437939, 2022). "Primary immunodeficiency was specifically inhibited (p = 0.0041), reflecting the up regulation of Cd8 (marker for cytotoxic T cells), Cd3δ, Cd3ε (required for differentiation of pro-T cells into pre-T cells) and Lck (required for Cd4+Cd8+ T cell differentiation into Cd8+ T cells)." (PMID 27515027, 2016). "The patient has a combined primary immunodeficiency with low levels of CD3, CD4 and CD19, and contrary to what we expected, his history of infections between 2017 and 2022 showed a controlled number of infections which were common to patients with CIVD." (PMID 37764964, 2023). "MFC data from CD4+ and CD8+ T cell subsets were examined in 100 patients referred for Primary Immunodeficiencies to our center." (PMID 31849946, 2019). "The patients with hematopoietic stem cell transplant, primary immunodeficiency and HIV had generally detectable and preserved spike‐specific CD4+ T‐cell responses, which have also been seen in both treatment‐naïve and immunochemotherapy‐treated individuals with lymphoma." (PMID 36825370, 2023).
primary immunodeficiency (continued). "One patient with MGUS diagnosis presented low improvement post-MV130 and is highly suspicious of being a primary immunodeficiency (PID) (lung linfangiomiomatosis, bronchiectasis, CD4+ T-cell lymphocytopenia), currently awaiting confirmation by genetic results and under IgRT treatment." (PMID 33679698, 2020). "Idiopathic CD4+ T lymphocytopenia is a rare condition, defined by a CD4+ T lymphocyte count of less than 300/mm3 (500-1500 cells/mm3) or less than 20% of total lymphocytes for at least six weeks, without evidence of acquired or primary immunodeficiencies." (PMID 38883060, 2024).
psoriatic arthritis (33 papers, 2005 to 2025). Joint inflammation associated with psoriasis. "Quantitative imaging by pixel-based contrast-enhanced ultrasound reveals a linear relationship between synovial vascular perfusion and the recruitment of pathogenic IL-17A-F+IL-23+ CD161+ CD4+ T helper cells in psoriatic arthritis joints." (PMID 33195301, 2020). "LAG-3, an immune checkpoint receptor of the immunoglobulin superfamily, has been implicated in self-tolerance, as evidenced by studies showing reduced LAG-3+CD4+ T cells in patients with active psoriatic arthritis." (PMID 41023624, 2025). "Accordingly, contradictory results have been shown for the frequency of PD-1+ CD4+ T cells in patients with psoriatic arthritis compared to HCs, with some of them reporting decreased PD-1+ T-cell percentages." (PMID 38835766, 2024). "In agreement with our results, CD70 expression was upregulated on CD4+ Th cells isolated from the synovial fluid of patients with psoriatic arthritis." (PMID 35300124, 2022). "We analyzed the phenotype and cytokine expression in circulating CD8+ and CD4+ T cells in 69 subjects: 28 with cutaneous psoriasis, 15 patients with psoriatic arthritis, and 26 healthy subjects." (PMID 31350460, 2019). "We found that, in contrast to healthy PB CD4+ T cells, psoriatic arthritis and in particular RA-SF CD4+ T cells supported the development of a population of CD1c+ DCs." (PMID 25923217, 2016). "Here, we compared the expression of CD146 on CD4+T cells between healthy donors (HD) and patients with RA and SpA [ankylosing spondylitis (AS) or psoriatic arthritis (PsA)] and examined correlations with surface markers and cytokine secretion." (PMID 25113810, 2015). "Increased frequency of CD4+IL-17+ cells, but decreased frequency of CD4+IL-22+ T cells, in psoriatic arthritis synovial fluid compared to peripheral blood." (PMID 24286492, 2013). "CD4 T cell resistance to PD-1-mediated suppression is increased in RA and psoriatic arthritis (PsA), which may be partially due to the presence of sPD-1 in the inflammatory milieu." (PMID 38474367, 2024). "Here we present the most extensive dataset of chromatin conformation with matching gene expression and chromatin accessibility from primary CD4+ and CD8+ T cells to date, isolated from psoriatic arthritis patients and healthy controls." (PMID 39930543, 2025). "For instance, PD1 was differentially expressed on the CD4+ and CD8+ T cells between RA and psoriatic arthritis patients." (PMID 30842773, 2019). "Besides, previous analysis of data extracted from patients with RA, SLE, psoriatic arthritis, and JIA suggested enrichment and activation of CD4+ T cell subpopulation during disease pathogenesis." (PMID 36551949, 2022). "In the context of human PV and psoriatic arthritis, MAIT cells have been evaluated in skin samples and synovial fluid, respectively, using TRAV1-2, CD161 and IL-18Rα as surrogate markers that relatively accurately estimate CD8+ and DN, but not CD4+ and DP MAIT cells." (PMID 33343564, 2020).
autoimmune thyroid disease (32 papers, 2011 to 2026). Inflammatory disease of the thyroid gland due to autoimmune responses leading to lymphocytic infiltration of the gland. "In children with autoimmune thyroid diseases, the CD4+ CD25hi CD127low FOXP3+ sub-population was shown to be significantly reduced compared to healthy donors, while there was no significant change in the CD4+ CD25hi CD127low sub-population." (PMID 40804844, 2025). "Massive infiltration of T CD4+ lymphocytes is a key mechanism for thyroid cell destruction in autoimmune thyroid disease." (PMID 36339447, 2022). "Surprisingly, Se upregulated CD4+CD25+ regulatory T cells in iodine-induced autoimmune thyroiditis model of NOD.H-2h4 mice." (PMID 22400102, 2012). "Such a decreased expression of CD40L has indeed been observed in peripheral CD4+ T cells in autoimmune thyroid disease." (PMID 21297967, 2011). "For example, intrathyroidal CD4+CD25+ Treg cells from patients with autoimmune thyroid diseases were prone to apoptosis, which led to a local Treg-cell reduction." (PMID 21935395, 2011). "Experimental autoimmune thyroiditis in mice resulted in an increase in both the number and functional activity of CD4-positive Tfh, Th17, Th2, and Th1 cells, and a decrease in both in the number and function of CD19-positive B10 cells and CD4-positive Treg cells." (PMID 39949783, 2025). "This study aimed to compare the number of CD4/CD25/FOXP3 T regulatory cells in the different forms of autoimmune thyroid diseases and in the normal population, and to compare the number of CD4 + CD25 + FOXP3 + T regulatory cells between the different forms of AITD, HT, and GD." (PMID 41307767, 2025). "This study aimed to compare the number of CD4/CD25/FOXP3 T regulatory cells between the different forms of autoimmune thyroid diseases from one hand, and to compare the number of CD4 + CD25 + FOXP3 + T regulatory cells between the different forms of AITD and a control group on the other hand." (PMID 41307767, 2025). "In anti-tumor immunity, GM-CSF treatment increases the frequency of tumor-specific Th1 T cells, and, in experimental autoimmune thyroiditis, GM-CSF treatment has been shown to both enhance IL-6–dependent Th17 cell responses and increase the number of immunoregulatory CD4+CD25+ T cells." (PMID 35877763, 2022). "Excitingly, in experimental research, (CD4+ and CD25+) T cells have been found to be involved in the etiology of autoimmune thyroiditis." (PMID 36295508, 2022). "Expression of SLAMF1 was significantly increased in peripheral blood CD4+, T helper 17, and CD19+ B cells from autoimmune thyroid disease patients." (PMID 32746852, 2020). "The research in vitro and in vivo conducted in recent years confirmed a regulatory function of CD4+CD25+ lymphocytes, their key role in the immune response, and their participation in the development of autoimmune diseases of the thyroid." (PMID 26000316, 2015). "Clinicians caring for children who demonstrate marked CD4 recovery should maintain a low threshold for evaluating unexplained weight loss, palpitations, heat intolerance, or ocular features, as these may reflect autoimmune thyroid disease rather than infection or ART toxicity." (PMID 41551367, 2026). "In rats exposed to HFD, intrathyroidal lymphocytic cell infiltration was significantly enhanced, and at least consisted of clusters of CD4+, CD8 + and CD19 + lymphocytes, similar to the types of infiltrated inflammatory cells in experimental autoimmune thyroiditis." (PMID 35840950, 2022). "The frequency of FOXP3+ Tregs among CD4+ T cells was significantly higher in the patients with TS than in the HC regardless of the presence of thyroid autoimmunity." (PMID 26709833, 2015). "This suggests that the Treg frequency among CD4+ T cells increased in patients with TS regardless of the development of thyroid autoimmunity." (PMID 26709833, 2015). "An increased proportion of CD4 + CD25+ cells was also found in patients with autoimmune thyroiditis irrespective of age." (PMID 24006909, 2013).
autoimmune thyroid disease (continued). "In another study, the proportion of CD4 + CD25+ T cells was not different between newly diagnosed and untreated autoimmune thyroiditis patients compared to HC." (PMID 24006909, 2013).
Hashimoto thyroiditis (32 papers, 2012 to 2025). An autoimmune disorder caused by the production of autoantibodies against thyroid tissue. "It is well established that approximately 25% of PTC cases coexist with Hashimoto’s thyroiditis, a correlation supported by shared biomarkers, genetic mutations, and immune-mediated pathways involving Cd3+, Cd4+, and Th17 cells." (PMID 40004911, 2025). "Notably, CD4+ T-cell hyperactivation constitutes a key pathogenic mechanism in Hashimoto’s thyroiditis development." (PMID 41306776, 2025). "As it was shown in recent studies, autoreactive CD4+ T cells and CD8+ cytotoxic T cells, as well as plasma cells producing autoantibodies play a central role in Hashimoto thyroiditis, which is often associated with thyroid tumor development." (PMID 39936166, 2025). "The percentage of oligomannose N-glycans in CD4+CD25+ cells from Hashimoto’s thyroiditis patients was about twice as high as in the CD4+CD25- pool, while complex-type glycans were in HT2 group significantly more abundant in CD4+CD25- cells than in CD4+CD25+." (PMID 41030447, 2025). "In Hashimoto's thyroiditis, cell-mediated immune responses involving Th1 and CD4+ T helper lymphocytes are predominant." (PMID 40900474, 2025). "In conclusion, our study demonstrates for the first time that N-glycosylation of CD4+ cells is subject to a fundamental change in Hashimoto’s thyroiditis." (PMID 41030447, 2025). "Comparing Tregs between the control group and Hashimoto’s disease, A statistically significant difference in the percentage of CD4/CD25 cells between the two groups was found." (PMID 41307767, 2025). "In CD4 + T cells in Hashimoto thyroiditis, increased SphK1 produces more S1P, which activates the S1PR1-JAK2-STAT3 and S1PR1-mTOR-STAT3 pathways." (PMID 37858140, 2023). "In Hashimoto’s thyroiditis, T CD4+ lymphocytes, under the action of antigen presenting cells (APCs), activate RORγt through the JAK2/STAT3 pathway and differentiate into Th17 cells." (PMID 36339447, 2022). "In the etiology of Hashimoto thyroiditis excessively stimulated T CD4+ cells are known to play the most important role." (PMID 26000316, 2015). "In this study, we examined the expression of different STAT proteins in surgical samples from patients with lymphocytic thyroiditis, a disease characterized by diffuse infiltration of the thyroid gland with CD4+ and CD8+ T cells and plasmocytes." (PMID 22527947, 2012). "All 80 samples were divided into 4 groups on average: HC group (Healthy control group), HT group (Hashimoto thyroiditis CD4+T cell inactive group), TCC group(Hashimoto thyroiditis CD4+T cell activation), TCC + ETO group(Hashimoto thyroiditis CD4+T cell activation + Etomoxir group)." (PMID 39641893, 2025). "On the one hand, utoreactive CD4+T lymphocytes during Hashimoto’s thyroiditis attract B cells and CD8+T cells to the thyroid, which may lead to hypothyroidism and thyroid cell death as the condition progresses." (PMID 39641893, 2025). "The mitochondria of CD4+T cells in Hashimoto’s disease are likely dysfunctional." (PMID 36619550, 2022). "Hashimoto thyroiditis is characterized by T-cell mediated autoimmune response; serum concentrations of anti-TPO and anti-Tg vary the degree of thyroid hypofunction and cause intrathyroidal infiltration of B and T-cell CD4+ type 1 T helper cells." (PMID 35140907, 2021). "However, the role of IL-22+ and IL-17A+ CD4+ T cells in the pathogenesis of Hashimoto’s thyroiditis (HT) is not fully understood." (PMID 24404171, 2014). "These diseases may concur with Hashimoto's thyroiditis (HT), the most common cause of hypothyroidism, in polyglandular autoimmune syndrome type III b, since Hashimoto's thyroiditis and Crohn disease are CD4+T helper (Th) 1-polarized disorders, while UC is an atypical Th2-polarized disease." (PMID 31040825, 2019). "It revealed that the relative TL levels of CD4+ CD45RA+ and CD8+ CD45RA+ in patients with Hashimoto's thyroiditis were comparable to those of healthy individuals." (PMID 40907117, 2025).